MPEG1 (macrophage expressed 1)
Description:
Pore-forming protein involved in both innate and adaptive immunity. Plays a central role in antigen cross-presentation in dendritic cells by forming a pore in antigen-containing compartments, thereby promoting delivery of antigens for cross-presentation (By similarity). Also involved in innate immune response following bacterial infection; shows antibacterial activity against a wide spectrum of Gram-positive, Gram-negative and acid-fast bacteria. Reduces the viability of the intracytosolic pathogen L.monocytogenes by inhibiting acidification of the phagocytic vacuole of host cells which restricts bacterial translocation from the vacuole to the cytosol (By similarity). Required for the antibacterial activity of reactive oxygen species and nitric oxide (By similarity). [Macrophage-expressed gene 1 protein, processed form]: Pore-forming protein that plays a central role in antigen cross-presentation in dendritic cells by mediating delivery of antigens for cross-presentation (By similarity). Dendritic cells bridge innate and adaptive immunity by capturing exogenous antigens on MHC class-I molecules and presenting them to naive CD8(+) T-cells (By similarity). Acts by forming a pore in antigen-containing compartments, promoting the release of antigens into the cytosol, enabling generation of MHCI:peptide complexes and T-cell priming (By similarity).
Synonyms: Mpg-1; P-2; P2; MPS-1; MPG1; IMD77; MPS1
Tractability: Small molecule: a high-quality ligand is known. Antibody: UniProt places it where antibodies can reach, with high confidence; UniProt predicts a signal peptide or a membrane-spanning region; its Gene Ontology location is reachable by antibodies, with medium confidence. PROTAC: UniProt records ubiquitination sites on it; its protein half-life has been measured; a small molecule that binds it is known.
Gene: Protein-coding gene on chromosome 11 (59,208,510 to 59,213,474, reverse strand). Ensembl gene ENSG00000197629.
Subcellular location: Cytoplasmic vesicle membrane (Isoform 1); Cytoplasmic vesicle, phagosome membrane (Macrophage-expressed gene 1 protein, processed form); Secreted (Isoform 2)
Gene Ontology:
Molecular function: wide pore channel activity
Biological process: defense response to bacterium; defense response to Gram-negative bacterium; defense response to Gram-positive bacterium; antibacterial innate immune response; antigen processing and presentation of exogenous peptide antigen; antigen processing and presentation of exogenous peptide antigen via MHC class I; dendritic cell antigen processing and presentation; transmembrane transport
Cellular component: cytoplasmic vesicle; cytoplasmic vesicle membrane; extracellular region; phagolysosome membrane; phagocytic vesicle; phagocytic vesicle membrane
Genetic constraint (gnomAD): Loss-of-function variants: 3 observed, 1.68 expected, observed/expected ratio (o/e) 1.78, 90% interval 0.62 to 1.94. That is too few expected variants to judge how well the gene tolerates losing a copy. Missense variants: 876 observed, 921.03 expected, observed/expected ratio (o/e) 0.95, 90% interval 0.9 to 1.01. Synonymous variants: 365 observed, 365.29 expected, observed/expected ratio (o/e) 1, 90% interval 0.92 to 1.09.
Homologues: Orthologues: chimpanzee MPEG1 (99% identical), macaque MPEG1 (88% identical), rabbit MPEG1 (83% identical), pig MPEG1 (78% identical), mouse Mpeg1 (76% identical), rat Mpeg1 (75% identical), guinea pig MPEG1 (69% identical), rat Pfpl (62% identical), mouse Pfpl (61% identical), zebrafish mpeg1.1 (49% identical), zebrafish mpeg1.2 (46% identical), zebrafish mpeg1.3 (43% identical).
Diseases named in the same sentence as MPEG1 in open-access papers:
MPEG1 is named in the same sentence as 43 diseases in open-access papers, as found by Europe PMC text mining. Sharing a sentence is not in itself a finding about the gene and the disease. The quoted sentences say what the papers report.
Obesity (3 papers, 2016 to 2022). Accumulation of substantial excess body fat. "We were able to further confirm the notion, that obesity alters satellite cell numbers and negatively affects the expression levels of Ankrd1, C3ar1, Ccl8, Mpeg1, and Myog, as seen in our qPCR results." (PMID 29922174, 2018). "For the identified DEHGs for obesity, there were six previously reported genes (UGGT1, ANO6, MPEG1, PTGS1, CLU and IQGAP1) and two novel genes (LUZP6 and PLCB2) for obesity." (PMID 35568907, 2022).
Sepsis (3 papers, 2015 to 2025). Sepsis is defined as life-threatening organ dysfunction caused by a dysregulated host response to infection. "A six-gene panel including EOMES, LTF, CSF1R, HLA-DRA, IRF8 and MPEG1 was discovered and validated with a high accuracy both in sepsis subjects and sepsis-induced ARDS subjects." (PMID 37443002, 2023). "The decreasing of macrophage-specific marker (MPEG1) and major histocompatibility complex, class II, DR alpha (HLA-DRA) in sepsis patients and ARDS patients were consistent with these findings." (PMID 37443002, 2023). "Four genes of them were differential expressed among sepsis-alone group, sepsis-induced ARDS group and controls, which were CSF1R, HLA-DRA, IRF8 and MPEG1." (PMID 37443002, 2023).
viral infection (3 papers, 2021 to 2025). "In antiviral immunity, cytokines induce the expression of MPEG1 to resist viral infection." (PMID 40692872, 2025).
hepatocellular carcinoma (2 papers, 2020 to 2022). A malignant tumor that arises from hepatocytes. "Macrophage-expressed gene 1 (MPEG1) was downregulated in hepatocellular carcinoma patients with poor prognosis." (PMID 35646056, 2022). "The depletion of MPEG1 could impact cell mitosis, disturb centrosome duplication, as well as induce chromosome misalignment and mis-segregation in hepatocellular carcinoma." (PMID 33169786, 2020).
abscesses (1 paper, 2020). "A young adult female patient was evaluated for recurrent abscesses and cellulitis of the breast and demonstrated a heterozygous, rare variant in MPEG1 p.Tyr430*." (PMID 33224153, 2020).
amyloid (1 paper, 2023). "These genes, Thy1, Gfap, Tyrobp, Ctsd, Cst7, C1qb, Lyz2, Ctss, Trem2, Mpeg1, Hexb, Cd68, C1qb, C1qa, Ctsz, Grn, Laptm5, B2m, C1qc, Hexa, and Serpina3n, were increased in the 7-month-old 5XFAD model in the cortex and associated with amyloid plaque image patterns." (PMID 38036733, 2023).
chlamydial infection (1 paper, 2020). "MPEG1 is inducible with IFNγ and type I interferons, both of which play important roles in limiting chlamydial infection in vivo." (PMID 32760406, 2020).
experimental autoimmune encephalomyelitis (1 paper, 2021). An autoimmune demyelinating disease of the central nervous system that is produced experimentally in animals by the injection of homogenized brain or spinal cord in Freund's adjuvant. "Likewise, microglia activation also begins early in disease development as RNAseq demonstrated that Mpeg1, a macrophage marker expressed also in microglia, was DE in 1-month Mcoln1−/− mice, as was Cxcl10, whose levels are also altered in models of experimental autoimmune encephalomyelitis." (PMID 33478506, 2021).
pulmonary mycobacterial infections (1 paper, 2020). "Furthermore, germline mutations in MPEG1 have been identified in connection with recurrent pulmonary mycobacterial infections in humans." (PMID 33178209, 2020).
rheumatoid arthritis (1 paper, 2025). A chronic, systemic autoimmune disorder characterized by inflammation in the synovial membranes and articular surfaces. "In addition, expression levels of Mpeg1, Enpp2, Tlr2, CD14, and Lyz2 were examined in the synovial tissues of patients with rheumatoid arthritis (RA) and persistent inflammatory, recurrent, and relapsing arthritis (PIRRA)." (PMID 40787440, 2025).
Sandhoff disease (1 paper, 2007). A lysosomal disorder from the GM2 gangliosidosis family, caused by biallelic pathogenic variants in the HEXB gene, characterized by GM2 ganglioside accumulation in the nervous system and progressive central nervous system degeneration. "In the Sandhoff disease mouse model, microglial activation was shown to precede neurodegeneration and was associated with upregulation of macrophage markers CD68/macrosialin, galectin 3, cathepsins S and C, Mpeg1, and glycoprotein49a, which we also observed." (PMID 18021406, 2007).
infection (50 papers, 2011 to 2025). The state of being infected such as from the introduction of a foreign agent such as serum, vaccine, antigenic substance or organism. "Studies of Mpeg1 knockout mice have shown that deficiencies in this protein lead to uncontrolled, disseminated infection from the gut and skin, as well as a host of other immunologic consequences." (PMID 33224153, 2020). "Further investigation will be required to assess if treatment with IFN-γ promotes perforin-2-mediated bactericidal activity and reduces infections in MPEG1 deficiency." (PMID 33224153, 2020). "In vertebrates, MPEG1-deficient mice and zebrafish are more susceptible to infections (by Methicillin-resistant Staphylococcus aureus, Salmonella typhimurium and Mycobacterium marinum) compared to wild-type counterparts." (PMID 33178209, 2020). "MPEG1 -/- mice are more susceptible to systemic listeriosis and succumb to sublethal doses of S. aureus and Salmonella in cutaneous and orogastric infection models, respectively." (PMID 32760406, 2020). "Its function in innate immunity is vital for intracellular pathogen elimination such that Mpeg1 knockout mice exhibit increased susceptibility to infections." (PMID 33224153, 2020). "This case expands the phenotype of MPEG1 deficiency to include severe skin and soft tissue infection." (PMID 33224153, 2020). "MPEG1 variants can confer an immunodeficiency hallmarked by polymicrobial infections." (PMID 33224153, 2020). "The association of these mutations with recurrent infections suggests there may be subtle clinical outcomes in individuals with a defective form of MPEG1; however, further clinical data is required to definitively implicate MPEG1 in these pathologies." (PMID 33178209, 2020). "We then analyzed the expression of the genes encoding Mpx and Mpeg1 in the infection site." (PMID 30143654, 2018). "In aggregate studies across species of invertebrates and bony fish have shown that infection and/or PAMPs induce the expression of Mpeg1." (PMID 33692780, 2021). "Curiously, Mpeg1 knockdowns survive infections longer than control embryos despite greater bacterial burden." (PMID 33692780, 2021). "It was also observed that Mpeg1.2 has a greater antibacterial contribution than Mpeg1 which is consistent with their expression patterns during infection." (PMID 33692780, 2021). "The overall downregulation of genes following infection of BALB/c mice is dominated by Mpeg1 and Pttg1." (PMID 33816350, 2021). "Consistently, the suppression of an MPEG1 paralog in zebrafish was observed to reduce the likelihood that fish would succumb to infection." (PMID 33178209, 2020). "Mice without MPEG1, which contained a single hypermethylated CpG site in TI calves and two hypermethylated CpG sites in PI heifers, are also more susceptible to infection by inhibiting early transcription and replication of viral RNA." (PMID 40316897, 2025). "Additional experimentation is required to clarify the roles of Mpeg1 and Mpeg1.2 during infection." (PMID 33692780, 2021). "Mpeg1 mRNA was significantly upregulated in the brain, head kidney, heart, liver, intestine, and spleen of the starry flounder Platichthys stellatus following infection with Streptococcus parauberis." (PMID 33692780, 2021). "In both cases all Mpeg1 −/− mice succumbed to infection within 15 days of inoculation." (PMID 33692780, 2021). "Given this protein domain analysis and phylogenetic information, understanding if the genes associated with Mpeg-1 are expressed in response to an active infection or a synthetic immune stimulus would further bolster our hypothesis that Cnidaria possesses functional Mpeg-1/P2." (PMID 32849589, 2020). "More importantly, we show increases in the mRNA expression levels of B cell (i.e., IgT, IgM, and IgD), T helper cell (i.e., CD4-1, CD4-2, and TCRα), and macrophage (i.e., MHC-II, MPEG1, and CSF1R) markers in trout SB upon infection with IHNV." (PMID 35379790, 2022).
infection (continued). "Instead, RSFR, MPEG1, ITGLB2 and HCLS1 were suppressed in HD11 cells 24 h after infection with wild type S. Enteritidis." (PMID 26380970, 2015). "Although infection or PAMP induced expression of Mpeg1 suggests Perforin-2 plays a role in host defense, Mpeg1 downregulation following bacterial infection may be indicative of bacterial countermeasures." (PMID 33692780, 2021).
bacterial infection (9 papers, 2015 to 2025). "Firstly, MPEG1 was down-regulated 256-fold, potentially increasing susceptibility to bacterial infection by decreasing the pro-inflammatory response." (PMID 39510801, 2025). "MPEG1 was down-regulated; this is normally induced in response to pro-inflammatory stimuli, with its loss linked to increased susceptibility to bacterial infection." (PMID 39510801, 2025). "Although Mpeg1 and Mpeg1.2 are inversely expressed during bacterial infections, both genes produce antibacterial responses." (PMID 33692780, 2021). "MPEG1 expression is induced by proinflammatory signals in several dozen cell lines and, furthermore, multiple cell lines succumb to bacterial infection when MPEG1 is knocked-down or knocked-out." (PMID 33178209, 2020). "Likewise embryos treated with Mpeg1.2 morpholinos succumb to bacterial infection significantly earlier than Mpeg1 knockdowns and controls." (PMID 33692780, 2021). "Curiously, the same bacterial infections inhibit Mpeg1 expression." (PMID 33692780, 2021). "Similarly, in Zebrafish one of its two isoforms, MPEG1.2, is induced following bacterial infection and limits bacterial burden." (PMID 26402460, 2015). "Nonetheless, we could speculate that the expression of Ct-Mpeg1 could be significantly upregulated after bacterial infection, as this is not the case in other species." (PMID 36362196, 2022).
cancer (7 papers, 2019 to 2025). A tumor composed of atypical neoplastic, often pleomorphic cells that invade other tissues. "MPEG1 (macrophage-expressed gene 1) is observed to be overexpressed in multiple human cancer tissues, including breast, liver, pancreas, lung and thyroid." (PMID 33169786, 2020). "MPEG1 is overexpressed in several human cancer tissues, including pancreas, breast, lung, liver, and thyroid." (PMID 31215439, 2019). "Analysis of cluster-specific genes indicates that these clusters correspond to cancer cells (GFP, Crabp1, Ank), myeloid cells (Aif1, Ctsc, Mpeg1), lymphoid cells (Il2rb, Cd28, Cd3e/g/d, Cd37), and stromal cells (Col1a1/2, Lum, Eln, Dpt), respectively." (PMID 41280683, 2025).
MPEG1 also shares sentences with these, for which no sentence is quoted: tumor (15 papers); melanoma (4); skin infection (2); bacteremia (1); bladder cancer (1); breast carcinoma (1); calculus (1); cardiac arrest (1); cellulitis (1); CNS lymphomas (1); Constipation (1); demyelination (1); diabetes (1); diabetic nephropathy (1); enteritis (1); fungal infections (1); Granuloma (1); immune disorders (1); infectious disease (1); inflammatory bowel disease (1); monocytic leukemia (1); Multiple Organ Failure (1); neurodegenerative disease (1); oral cancers (1); Salmonella Infections (1); scoliosis (1); Stroke (1); thyroid cancer (1); Yersinia pseudotuberculosis infection (1).